YIPF7 (Yip1 domain family member 7)
Synonyms: FINGER9; YIP1B; FLJ39576; YIPFalpha1b
Tractability: Antibody: UniProt predicts a signal peptide or a membrane-spanning region.
Gene: Protein-coding gene on chromosome 4 (44,622,088 to 44,678,795, reverse strand). Ensembl gene ENSG00000177752.
Subcellular location: Endoplasmic reticulum membrane; Golgi apparatus, cis-Golgi network membrane; Golgi apparatus, trans-Golgi network membrane
Gene Ontology:
Biological process: endoplasmic reticulum to Golgi vesicle-mediated transport; vesicle fusion with Golgi apparatus
Cellular component: endoplasmic reticulum membrane; cis-Golgi network; endomembrane system; endoplasmic reticulum-Golgi intermediate compartment; Golgi apparatus; membrane
Genetic constraint (gnomAD): Loss-of-function variants: 28 observed, 22.22 expected, observed/expected ratio (o/e) 1.26, 90% interval 0.93 to 1.71. The synonymous counts are far from expectation, so gnomAD's model fits this gene poorly and the ratio says little. Missense variants: 338 observed, 277.57 expected, observed/expected ratio (o/e) 1.22, 90% interval 1.11 to 1.33. Synonymous variants: 131 observed, 103.18 expected, observed/expected ratio (o/e) 1.27, 90% interval 1.1 to 1.47.
Homologues: Orthologues: chimpanzee YIPF7 (98% identical), rabbit YIPF7 (87% identical), pig YIPF7 (84% identical), rat Yipf7 (83% identical), guinea pig YIPF7 (82% identical), mouse Yipf7 (81% identical), dog YIPF7 (79% identical), tropical clawed frog yipf7 (61% identical), zebrafish zgc:123321 (56% identical), Drosophila melanogaster Yip1d1 (44% identical), Caenorhabditis elegans F32D8.14 (41% identical). Paralogues in human: YIPF5 (62% identical), YIPF4 (23% identical), YIPF6 (21% identical).
Diseases named in the same sentence as YIPF7 in open-access papers:
YIPF7 is named in the same sentence as 2 diseases in open-access papers, as found by Europe PMC text mining. Sharing a sentence is not in itself a finding about the gene and the disease. The quoted sentences say what the papers report.
colorectal cancer (1 paper, 2017). A primary or metastatic malignant neoplasm that affects the colon or rectum. "Immunohistochemical analyses for NAALADL2 and YIPF7 were performed using inflamed colon tissues obtained from patients with intestinal BD or IBD and normal colon tissues obtained from patients with colorectal cancer after intestinal surgery." (PMID 28045058, 2017).
YIPF7 also shares sentences with these, for which no sentence is quoted: Crohn disease (1 paper).